VDR (vitamin D receptor)
Diseases named in the same sentence as VDR in open-access papers (continued):
Sharing a sentence is not in itself a finding about the gene and the disease.
glioma (12 papers, 2009 to 2026). A benign or malignant brain and spinal cord tumor that arises from glial cells (astrocytes, oligodendrocytes, ependymal cells). "Consistent with the TCGA data, the protein expression level of the VDR gene in most of patient‐derived glioma cell lines tested was also relatively lower." (PMID 37489660, 2023). "BNI274 and G98, which had relatively higher VDR expression levels in patient‐derived glioma cell lines, were selected for a VDR‐knockdown assay by shRNA." (PMID 37489660, 2023). "The aim of our study was to determine a possible relationship between Vitamin D receptor (VDR) gene polymorphisms and the risk of glioma and meningioma." (PMID 23691496, 2013). "Other CNS pathologies affecting glia and showing VDR over-expression include astrocytomas, gliomas and reactive astrocytosis in mice." (PMID 19426536, 2009). "Vitamin D3-induced VDR expression was reported in glioma cells U251, U-87 MG, and T98G." (PMID 40920750, 2025). "We observed that VDR does not affect the sensitivity of patient‐derived glioma cell lines to vitamin D3, and the gene encoding VDR is not essential for growth of patient‐derived glioma cell lines." (PMID 37489660, 2023). "Thus, H19 inhibits glioma cell apoptosis through the H19/miR-675/VDR feedback loop." (PMID 38355574, 2024). "Notably, VDR has been found to protect against glioma by inducing apoptosis." (PMID 38355574, 2024). "Compared with other common cancers, gliomas, including GBM and low‐grade gliomas, had relatively low mRNA expression of VDR." (PMID 37489660, 2023). "In summary, these results showed that the VDR was not an essential gene for patient‐derived glioma cell lines, nor did it affect the inhibitory effect of vitamin D3 on patient‐derived glioma cell lines." (PMID 37489660, 2023). "Such evidence supports the hypothesis that the inhibitory effects of vitamin D3 and vitamin D2 on patient‐derived glioma cell lines were not obtained through VDR." (PMID 37489660, 2023). "Such evidence supports our hypothesis that the inhibitory effects of vitamin D3 on patient‐derived glioma cell lines were not obtained through VDR." (PMID 37489660, 2023).
Graves disease (12 papers, 2009 to 2025). Graves' disease is an autoimmune disorder that leads to overactivity of the thyroid gland (hyperthyroidism).It is caused by an abnormal immune system response that causes the thyroid gland to produce too much thyroid hormones. "Gao and Yu’s meta-analysis included 24 independent studies on the association between the risk of autoimmune thyroid diseases (Graves’ disease and HT) and the VDR polymorphisms rs731236 (TaqI), rs1544410 (BsmI), rs2228570 (FokI) and rs7975232 (ApaI)." (PMID 41226614, 2025). "Recent studies have investigated genetic susceptibilities for the development of Graves’ disease associated with specific variants of single nuclear polymorphisms (SNPs) in VDR genes." (PMID 31913301, 2020). "Japanese studies reported an association between VDR FokI polymorphism, Hashimoto’s Thyroiditis and Graves’ disease." (PMID 27011770, 2016). "For example, vitamin D receptor (VDR) gene polymorphisms were found to be associated with the risk for Graves’ disease." (PMID 26007334, 2015). "The VDR polymorphisms were also connected to Graves’ disease in the Polish population." (PMID 39859195, 2025). "Moreover, VDR gene polymorphisms affect immune response in immune-related diseases such as Graves' disease and SLE." (PMID 33226370, 2020). "Second, we did not compare the vitamin D levels of patients with Graves’ disease with those of healthy controls or consider the genetic aspects of vitamin D function, such as VDR gene expression; however, these topics were beyond the scope of our study." (PMID 31913301, 2020). "It cannot be excluded that the role of VDR gene variants is not the same in two phenotypes of AITD-AIT and Graves' disease." (PMID 31531369, 2019).
liver cirrhosis (12 papers, 2013 to 2024). "Polymorphisms of the VDR gene were associated with the development of HCC in patients with liver cirrhosis." (PMID 37175993, 2023). "Here, we investigated the association between BsmI, ApaI, TaqI and FokI VDR polymorphisms and the severity of liver cirrhosis in relation to serum cytokine and lipopolysaccharide binding protein (LBP) levels and their role on survival in cirrhotic patients." (PMID 30218108, 2018). "In particular, an independent association between BsmI, ApaI, and TaqI VDR polymorphisms and the severity of liver cirrhosis is clearly shown." (PMID 30218108, 2018). "The authors concluded that VDR genetic polymorphisms are significantly associated with the occurrence of HCC in patients with liver cirrhosis, and this relationship is more specific for patients with an alcoholic etiology." (PMID 23586065, 2013). "In addition, the polymorphism of VDR in immune cells and hepatocytes also presents a high correlation with liver cirrhosis, owing to the co-mediation of VDR and bile salts for vitamin D uptake." (PMID 37426183, 2023). "In this study, we have investigated the potential associations between VDR gene polymorphisms and the severity of liver cirrhosis, in relation to the cytokine and bacterial profiles, vitamin D and vitamin D binding protein (VDBP) levels, and their role on patient survival." (PMID 30218108, 2018). "Moreover, our recent study indicated the relationship between the BsmI and TaqI polymorphisms of the VDR gene and the presence of liver cirrhosis and advanced fibrosis." (PMID 28426778, 2017). "In a flow cytometry analysis of VDR expression on PBMCs in patients with liver cirrhosis, hepatitis C virus positive patients, and healthy controls, median fluorescence intensity was higher for VDR expression on CD14+ cells compared to CD3+ cells." (PMID 39409006, 2024). "It is noteworthy that, VDR rs3782905 CC and DBP rs7041 TG genotypes are more associated with a higher risk of HCV-induced liver cirrhosis than with HCC progression in HCV-infected patients." (PMID 38066559, 2023). "In this study, we investigated the role of VDR in liver cirrhosis and HCV infection, focusing on the influence of the SNPs ApaI, BsmI, TaqI, and FokI in the VDR gene." (PMID 37511164, 2023). "The concentrations of 25(OH)-VD3 and VDR were remarkably attenuated in rat and human serum of liver cirrhosis, and in contrast, augmented levels of CYP24A1 were detected compared with the control group." (PMID 37273916, 2023). "A significant linkage has been found to exist between VDR polymorphism and incidence of HCC among liver cirrhosis patients." (PMID 29449867, 2018). "There is significant linkage between VDR polymorphism and incidence of HCC among liver cirrhosis patients." (PMID 29449867, 2018). "However, we have previously reported that by 6 months of age, some whole-body VDR null mice develop spontaneous liver cirrhosis." (PMID 38963813, 2024). "More importantly, supraphysiological concentrations of 25(OH)D3 resulting from artificial vitamin D supplementation can act as a VDR agonist, inhibiting Hedgehog (Hh) pathway, reducing the production of hepatitis C virus (HCV) largely, blocking an important predisposing factor for liver cirrhosis." (PMID 37426183, 2023). "The increased VDR expression in T lymphocytes from cirrhotic patients with the CC genotype of the FokI SNP may reflect a positive influence of FokI SNP on the immunomodulatory and antifibrotic activity of the vitamin D-VDR pathway in liver cirrhosis." (PMID 37511164, 2023). "It is noteworthy that, VDR rs3782905 CC and DBP rs7041 TG genotypes are higher in HCV induced liver cirrhosis than with HCC progression in HCV infected patients." (PMID 38066559, 2023). "The levels of CD3+VDR+ and CD14+VDR+ cells were significantly increased in HCV+ patients and patients with liver cirrhosis compared with healthy controls." (PMID 37511164, 2023).
liver cirrhosis (continued). "Enzyme-linked immunosorbent and reverse transcription PCR (RT-PCR) analysis were used to determine the levels of 25(OH)-VD, vitamin D receptor, Cytochrome P450 24A1 (CYP24A1), and α-defensin 5 (DEFA5) in rat and human serum of liver cirrhosis." (PMID 37273916, 2023). "We measured the levels of 25(OH)-VD3, VDR, and CYP24A1 in the ileum of rats and the serum of liver cirrhosis patients." (PMID 37273916, 2023). "The expressions of 25(OH)-D3 and VDR decreased while that of 1,25-dihydroxyvitamin D 24-hydroxylase (CYP24A1) was increased in intestinal tissues of liver cirrhosis rats." (PMID 37273916, 2023).
cognitive disorder (11 papers, 2018 to 2025). A disease affects cognitive processes. "Vitamin D receptor (VDR) gene polymorphisms in humans have been associated with cognitive impairment and depressive symptoms." (PMID 29649128, 2018). "As a matter of fact, the depletion of vitamin D and the vitamin D receptor is fundamental for mitochondria activity, and this can surely help to explain why vitamin D is fundamental to preventing cognitive disorders, such as those occurring in AD." (PMID 36671042, 2023). "In another study that compared the frequency of GG versus AA and AG genotypes, the association with insufficient 25(OH)D concentrations was maintained, suggesting that BsmI, which regulates VDR expression, can modulate vitamin D levels in patients with cognitive disorders." (PMID 37630755, 2023). "Whether there VDR expression is altered in the hippocampus and in particular in the neurogenic zones of hippocampus of PD patients with or without cognitive impairment is presently unknown." (PMID 29467625, 2018).
colorectal adenoma (11 papers, 2012 to 2025). An adenoma that arises from the colon or rectum. "In summary, this study identifies the b allele of the VDR-BsmI gene as a significant risk factor for colorectal adenoma (CRA) in the Romanian population, highlighting its association with earlier diagnosis." (PMID 39201651, 2024). "Furthermore, plasma concentration of 25-Hydroxyvitamin D3 (25(OH)D) has been found to correlate with risk of developing colorectal adenoma and adenocarcinoma and lower expression of vitamin D receptor (VDR) has been observed in colorectal adenocarcinoma cells as compared to adjacent normal tissue." (PMID 35681576, 2022). "Complicating the matter, an RCT in colorectal adenoma reported that the beneficial effect of vitamin D3 supplementation varies with VDR genotypes." (PMID 40732958, 2025). "We investigated the prevalence of the VDR-BsmI (rs1544410) and NsiI A/G-INSR (rs2059806) polymorphisms and their associations with colorectal adenoma (CRA) in a Romanian population." (PMID 39201651, 2024). "The levels of VDR mRNA expression in colorectal adenoma and adenocarcinoma tissues are lower than those in normal tissues." (PMID 38329439, 2024). "This includes exploring how VDR polymorphisms, such as BsmI, and INSR polymorphisms, such as NsiI A/G, influence the transition from colorectal adenoma to carcinoma." (PMID 39201651, 2024). "A previous study showed that the effect of vitamin D3 supplementation on advanced colorectal adenomas varied according to vitamin D receptor genotypes." (PMID 31466528, 2019). "Beyond the gynecological field, VDR upregulation has also been described in colorectal adenomas and nasal polyps, supporting the notion that this receptor’s increased expression may represent a conserved feature across benign proliferative disorders." (PMID 41394244, 2025). "However, others have reported an inverse association between circulating 25(OH)D levels and colorectal adenoma risk, but not with VDR gene polymorphisms (Folk and Bsml)." (PMID 40732958, 2025). "Importantly, increased VDR expression has been documented in various benign proliferative lesions, including colorectal adenomas and nasal polyps, suggesting upregulation may represent an intrinsic protective mechanism against uncontrolled growth." (PMID 41394244, 2025). "Furthermore, a recent RCT study suggested that the benefit of supplementary vitamin D intake in preventing advanced colorectal adenomas may vary according to different VDR." (PMID 36091680, 2022). "Since vitamin D supplementation reduces oxidative DNA damage induced by alkylating agents in the colonic mucosa of patients with colorectal adenoma, we hypothesized that an increase of tumor initiation/progression in VDR KO mice may resulted from enhancement of AOM-induced oxidative DNA damage." (PMID 27768599, 2016).
migraine (11 papers, 2013 to 2025). "It is interesting to know that VDR gene polymorphism has been studied with migraine and susceptibility for cluster headache development due to altered clinical phenotypes in the Caucasian populations." (PMID 38699683, 2024). "Genotype frequency distribution analysis between migraine subtypes and control subjects revealed significant associations for all three investigated VDR variants with MwoA susceptibility." (PMID 37755360, 2023). "The VDR rs731236A allele showed a significant association with the triggering of migraine attacks by ethanol (Pc = 0.007)." (PMID 37553799, 2023). "In conclusion, the findings of the current study further support a possible association of SNVs in VDR with the susceptibility to develop migraine and MwoA subtype." (PMID 37755360, 2023). "On the other hand, subjects carrying the minor allele of VDR rs731236 SNV showed a lower frequency of induction of migraine attacks by ethanol, being this finding difficult to explain." (PMID 37553799, 2023). "The Hardy–Weinberg equilibrium was fulfilled by the frequencies of the genotypes and allelic variants of VDR rs2228570, VDR rs731236, VDR rs7975232, VDR rs739837, VDR rs78783628, GC rs7041, and GC rs4588 SNVs, both in migraine patients and in controls." (PMID 37553799, 2023). "Two previous studies addressed the possible relationship between VDR or GC variants and the risk for migraine." (PMID 37553799, 2023). "To date, only two studies have investigated the association between VDR SNVs and migraine susceptibility in diverse populations." (PMID 37755360, 2023). "Dysfunction of vitamin D-binding protein and polymorphism of the vitamin D receptor gene have been reported in patients with migraine, while the relationship between the serum vitamin D level and headache frequency in migraine patients is controversial." (PMID 30019090, 2018). "The aim of this study was to investigate the association between migraine and two vitamin D receptor (VDR) polymorphisms (TaqI and FokI) and also the relationship between VDR polymorphisms and headache severity.Methods." (PMID 23984350, 2013). "Further, Iranian patients with migraine also had TaqI and FokI VDR gene polymorphisms." (PMID 38699683, 2024). "Two single‐nucleotide variants (SNVs) vitamin D receptor (VDR) gene, VDR rs2228570, and VDR rs731236 have shown an association with migraine risk in a previous case–control association study, while an exome sequencing study identified a rare variant in GC vitamin D binding protein gene." (PMID 37553799, 2023). "The aim of the study was to investigate the relation of the three most studied VDR variants, i.e., FokI (rs2228570), TaqI (rs731236) and BsmI (rs1544410), with migraine susceptibility and distinct clinical phenotypes in a Southeastern European case-control population residing in Greece." (PMID 37755360, 2023). "Heterozygosity for the VDR TaqI (TC) and BsmI (GA) variants may serve as a risk factor for migraine and MwoA susceptibility in the studied Southeastern European population." (PMID 37755360, 2023). "Also, the effect of vitamin D receptor gene polymorphism should be clarified when studying the potential role of vitamin D supplementation in improvement of migraine characteristics and disability level." (PMID 32093657, 2020). "Although these interesting findings do not provide definitive evidence for a causal association between VDR gene and migraine, the VDR has a broad expression in the central nervous system, where the binding to its agonists produces an important (pleiotropic) anti-inflammatory effect." (PMID 24900990, 2014). "Consequently, variability in the VDR gene may serve as a genetic susceptibility factor for migraine and MwoA subtype in Southeastern Europeans." (PMID 37755360, 2023).